MTOR (mechanistic target of rapamycin kinase)
Diseases named in the same sentence as MTOR in open-access papers (continued):
Sharing a sentence is not in itself a finding about the gene and the disease.
colon carcinoma (continued). "To investigate the impact of drugs on blocking mTOR signaling, we measured, by Western blot, the expression of phospho-S6RPSer235/236 (an mTORC1 effector) in colon cancer cell lines treated for 24 h with rapamycin, AZD2085, and AZD2014, at concentrations ranging from 50 to 500 nM." (PMID 31627299, 2019). "In the present study, we showed that catalytic mTOR inhibitors more effectively inhibited the viability of colon cancer cells than the allosteric inhibitor rapamycin, as rapamycin led to only a partial inhibition of the mTORC1 complex through a weak inhibition of 4EBP phosphorylation." (PMID 31627299, 2019). "mTOR is one of the important kinases that is deregulated in colon cancer." (PMID 30111296, 2018). "Finally, salidroside, a major phenylpropanoid glycosides found in Rhodiola rosea L., prevented tumour cachexia in CT-26 colon cancer and Lewis lung carcinoma and restored levels of muscle phospho-mTOR, used as a read-out of mTORC1 activity." (PMID 30061533, 2018). "This dual inhibition of mTOR is advantageous since mTOR inhibitors, were reported to induce multiple resistance mechanisms, particularly feedback activation of Akt which displays abnormal signaling in colon cancer." (PMID 30111296, 2018). "Similarly, everolimus, a specific mTOR inhibitor, reduced IL-6 levels and alleviated the cachectic phenotype of CT-26 colon cancer bearing mice in which IL-6 is the main cachectic driver." (PMID 30061533, 2018). "In the current study, we investigated whether InsP6 inhibits AKT/mTOR signaling cascade in Caco-2 colon cancer cells as a significant regulator of proliferation and apoptosis." (PMID 28972559, 2017). "Our data demonstrating the suppression of Akt and mTOR activation in colon cancer cells are consistent with suppression of the cell survival pathway and may support autophagic cell death." (PMID 28412728, 2017). "We recently reported that mTOR inhibitors induce apoptosis via ER stress and the extrinsic pathway upon acute inhibition of the eIF4F complex in colon cancer cells and xenografts, while mutant BRAF600E leads to therapeutic resistance via ERK-mediated Mcl-1 stabilization." (PMID 28030835, 2017). "Notably, the observed changes in cellular shape and size, which are similar to those reported in RSV-treated HeLa, colon cancer and ovarian cells, are apparently in contrast with the mTOR inhibition induced by RSV." (PMID 27649143, 2016). "For example, NDRG2, a kinase downstream of the mTOR/SGK pathway and a tumor suppressor that mediates apoptosis, and EMD, a nuclear membrane protein phosphorylated by Src, both preferentially bind HNF4α1 and have been negatively associated with colon cancer." (PMID 27166517, 2016). "Deregulation of mTOR signaling occurs in several human tumors including colon cancer." (PMID 25788964, 2015). "Many of the genetic alterations responsible for colorectal carcinogenesis act through the mTOR pathway, suggesting that mTOR inhibitors could be effective in preventing colon cancer progression." (PMID 26302180, 2015). "We have previously reported that AST inhibits colon cancer growth by its interaction with the PI3K-Akt-mTOR pathway, which may correlate with the complicated modulation of calpains." (PMID 25319833, 2014). "While screening synergistic drug combinations for colon cancer therapy, we identified a novel multidrug treatment for colon cancer: chemotherapeutic agent melphalan in combination with proteasome inhibitor bortezomib and mTOR (mammalian target of rapamycin) inhibitor rapamycin." (PMID 25356873, 2014). "Furthermore, the inhibition of the proteasome function represses mTOR signalling and protein translation in colon cancer cells." (PMID 23697803, 2013). "LS174T (PI3KCA mutation on exon 20), DLD-1 (PI3KCA mutation on exon 9) and SW480 (PI3KCA wild type) colon cancer cells were treated with increasing concentrations of rapamycin, PP242, a specific mTOR inhibitor, or NVP-BEZ235, a dual PI3K/mTOR inhibitor for six hours." (PMID 22401294, 2012).
colon carcinoma (continued). "Consistent with our findings, NVP-BEZ235 is effective in a mouse model of sporadic PI3KCA wild type CRC suggesting that the antitumor activity of ATP-competitive inhibitors of mTOR is not restricted to PI3KCA mutated colon cancer cells." (PMID 22401294, 2012). "Recently, studies identified rapamycin-mediated inhibition of PHLPP (PH domain leucine-rich repeats protein phosphatase) expression through a mTOR-dependent compensatory feedback loop may contribute to rapamycin resistance in colon cancer cells." (PMID 22428038, 2012). "In addition, it also shows that the anticancer efficacy of ATP-competitive inhibitors of mTOR is potentiated by the simultaneous pharmacological blockade of the MEK/MAPK signaling pathway in colon cancer cells." (PMID 22401294, 2012). "Therefore our results provide rationale for the clinical evaluation of ATP-competitive inhibitors of mTOR in colon cancer patients." (PMID 22401294, 2012). "Indeed, components of mTOR signaling pathways are frequently over-expressed and activated in human samples of colon cancer." (PMID 22401294, 2012). "To next investigate whether the effects induced by mTOR inhibitors on colon cancer cell growth result from a reduction of cell proliferation, we performed 5-bromo-2'-deoxyuridine (BrDU) incorporation assay." (PMID 22401294, 2012). "In addition, in experimental settings, the inhibition of mTOR components using siRNA or shRNA results in a marked reduction of colon cancer cell growth in vitro and tumor xenograft growth in vivo." (PMID 22401294, 2012). "Furthermore, targeting mTOR with a specific siRNA to mTOR also reduced SW480 and HCT116 colon cancer cell proliferation and survival in vitro and injection of small interfering RNA to mTOR into HCT116 tumor xenografts also blocked tumor growth in vivo." (PMID 20226010, 2010). "Hence, we sought to evaluate whether treating RKO colon cancer cells with the M36 inhibitor could also affect the activation rate of the Akt-mTOR and MAPK pathways." (PMID 38473963, 2024). "Thus, ginsenoside Rg1 induced autophagy via inhibiting the Akt/mTOR/p70S6K pathway in colon cancer." (PMID 38668684, 2024). "Studies have shown that butyrate may potentially yield advantageous effects in cancers such as colon cancer through the activation of autophagy, achieved by inhibiting the mTOR pathway, and propionate may also induce autophagy by downregulating the mTOR signaling pathway." (PMID 38369469, 2024). "Additionally, for LoVo colon cancer cells, irinotecan inhibits mTOR and activates the autophagy-related genes, ULK1, ATG13, ATG4L, and AMBRA1, promoting autophagy with increased numbers of lysosomes and lysosomal activity, which contribute to irinotecan resistance." (PMID 39456585, 2024). "Besides, ERβ could inhibit the mammalian target of rapamycin (mTOR) or activate Bcl‐2/adenovirus E1B 19‐kDa‐interacting protein 3 (BNIP3) to promote autophagy in colon cancer (HCT116) cells." (PMID 36207986, 2023). "The overexpression of miR-126-3p inhibits proliferation and mTOR expression and induces autophagy and apoptosis in colon cancer cells, which is reversed by autophagy inhibitor bafilomycin A1, suggesting that miR-126-3p-induced apoptosis depends on autophagy through the modulation of mTOR expression." (PMID 36835100, 2023). "Additionally, the PI3K/Akt/mammalian target of rapamycin (mTOR) pathway is highly activated in colon cancer stem cells and inhibiting this pathway reduces stem cell proliferation or spheroid formation; the stemness is reduced as indicated by decreasing expression of Lgr5, a cancer stem cell marker." (PMID 34163519, 2021). "Similarly, a recent report has shown that PL could suppress tumor cell growth and proliferation in DMH/DSS-induced experimental colon cancer by targeting Ras/PI3K/Akt/mTOR signaling axis." (PMID 33343354, 2020).
colon carcinoma (continued). "Moreover, it was reported that the combination of indol-3-carbinol (I3C; 300 μM), from cruciferous vegetables, and genistein (40 μM) inhibited the survival of human colon cancer HT-29 cells by inducing apoptosis and autophagy through the downregulation of Akt and mTOR." (PMID 32927836, 2020). "Two important studies analysed the types of colon cancers that responded to aspirin treatment, and discovered that only a subset of tumours were sensitive: those containing activating mutations of PI3KCA45, 46, which results in a constitutively upregulated PI3K/Akt/mTOR pathway." (PMID 28717171, 2017). "Based on the present studies it may be concluded that InsP6 can reduce proliferation and induce apoptosis through inhibition of AKT/mTOR pathway and mTOR effector followed by modulation of the expression and activity of several key components of this pathway in colon cancer cells." (PMID 28972559, 2017). "Based on these studies it may be concluded that InsP6 can reduce proliferation and induce apoptosis through inhibition of the AKT/mTOR pathway and mTOR effector followed by modulation of the expression and activity of several key components of these pathways in colon cancer cells." (PMID 28972559, 2017). "In colon cancers, the levels of mLST8 transcripts were elevated, suggesting that activation of some transcription factors and/or silencing of particular microRNAs may be involved in mLST8 upregulation, as observed for other components of the mTOR complexes." (PMID 25906254, 2015). "Taken together, these findings suggest that AST exerts anti-carcinogenic activity in colon cancer cells through modulation of mTOR signaling and downregulation of COX-2, which together reduce VEGF level in tumor cells that could potentially suppress angiogenesis." (PMID 22992293, 2012). "Finally, we also investigated whether mTOR inhibitors induce apoptosis of colon cancer cells by using a cell death detection ELISA." (PMID 22401294, 2012). "In colon cancer, GFAT inhibitors reduce O‐GlcNAcylation, suppressing mTOR activation, while OGA knockdown (KD) elevates O‐GlcNAcylation, enhancing mTOR signalling and tumour progression." (PMID 41540817, 2026). "Expression data from the oncoDB database indicate that the expression of PI3k is higher in colon cancer (n = 308) compared to normal tissues (n = 41), whereas the expression of AKT, mTOR and NF-κB genes showed lower expression." (PMID 41180483, 2025). "Another study implicated PDE4D in the suppression of the AKT-mechanistic target of rapamycin (mTOR)-MYC proto-oncogene, BHLH transcription factor (MYC) signaling pathway, reducing the malignant properties of colon cancer cells." (PMID 40961924, 2025). "Resistant starch inhibits mTOR and downregulates HK2 pathways, which are involved in the proliferation, growth, and metastasis of colon tumor cells." (PMID 41249064, 2025). "Polyphenols such as caffeic acid and derivatives have been shown to inhibit the growth of colon cancer cells and reverse doxorubicin resistance in BC cells via the AMPK/AKT/mTOR pathway modulation." (PMID 39064812, 2024). "As an ATP-competitive PI3K/mTOR dual inhibitor, gedatolisib (PF-04691502) has been utilized to inhibit tumor growth and CSC proliferation in both in vitro and in vivo colon cancer models." (PMID 39349424, 2024). "In colon cancer cells, vanillic acid exerts inhibitory effects on HIF-1alpha expression through the mTOR/p70S6K/4E-BP1 and Raf/MEK/ERK pathways." (PMID 39103210, 2024). "In colon cancer, miR-212 functions as it exerts a tumor suppressor effect by directly targeting PIK3R3 and modulating regulating the AKT/mTOR signaling pathway." (PMID 39133165, 2024). "In a study comparing 2D and 3D cultures of colon cancer cells, it was shown that PI3K/mTOR signaling was at lower levels in 3D cultures compared to 2D cultures." (PMID 39770404, 2024).
colon carcinoma (continued). "For instance, we have found NSC49L to be effective against colon cancer through the activation of PP2Ac and subsequently decreasing the AKT1/mTOR/4E-BP1 axis and p21 translation in FOLFOX-resistant colon cancer cells." (PMID 38184584, 2024). "Hesperidin triggered cell death in colon cancer-afflicted mice by suppressing the ongoing activation of the Aurora-A-driven PI3K/Akt/GSK-3β and mTOR pathways, thereby stimulating autophagy in this particular colon cancer model." (PMID 39201782, 2024). "Ursolic acid (UA) treatment significantly decreased the ARL4C protein level in human colon cancer and inhibited the AKT/mTOR signaling pathway." (PMID 39767779, 2024). "For example, in colon cancer, AA appears to regulate Pdcd4 through the PI3K/Akt/mTOR/p70S6K signaling pathways, which are well known to be the main pathways regulating proliferation, apoptosis, and migration of cancer cells." (PMID 38610995, 2024). "In agreement with this phenomenon, we previously demonstrated that the knockdown of p32/C1QBP inhibits mTOR activity in both RKO and SW480 colon cancer cells." (PMID 38473963, 2024). "The effects of the inhibitor of C1QBP were cytostatic and non-cytotoxic, inducing a decreased activation rate of critical pro-malignant and mitogenic cellular pathways such as Akt-mTOR and MAPK in RKO colon cancer cells." (PMID 38473963, 2024). "Meanwhile, we discovered that PI3K/AKT/mTOR signaling is the downstream pathway of the has_circ_0008234/miR-338-3p/ETS1 axis, which improves the effect network of circRNAs in colon cancer." (PMID 37046729, 2023). "Intriguingly, in colon cancer CT26 cells, DOP stimulated ROS production and reduced mitochondrial membrane potential (MMP) by activating AMPK/mTOR autophagy signaling, and finally disrupted mitochondrial function." (PMID 37812195, 2023). "In conclusion, we demonstrated that propofol inhibits the stemness and EMT of colon cancer cells by downregulating the SIRT1 and the Wnt/β-catenin and AKT/mTOR signaling pathways." (PMID 37490168, 2023). "For example, in HCT116 colon cancer cells, apigenin modulated the PI3K/Akt/mTOR signaling pathway to induce autophagy." (PMID 36901174, 2023). "Treatment of colon cancer cells with α-methyltryptophan (α-MT), a blocker of SLC6A14, decreases mTOR activity, triggers autophagy and promotes apoptosis." (PMID 37373349, 2023). "SHANK1 is abnormally and highly expressed in colon cancer; knockdown of SHANK1 inhibits the survival, proliferation, and migration of colon cancer cells through the AKT/mTOR signaling pathway." (PMID 35468874, 2022). "Gut epithelial TSC1/mTOR reduces necroptosis by inhibiting the expression and activation of RIPK3, thus preventing IBD and even colon cancer." (PMID 35884370, 2022). "OSI-027 is an inhibitor of mTOR downstream of PI3K and can inhibit colon cancer cell growth through the 4EBP1/eIF4E/PUMA pathway." (PMID 36414988, 2022). "Taken together, this study suggests that Lar significantly suppresses colon cancer proliferation and migration by activating AMPK/mTOR‐mediated autophagic cell death." (PMID 36251949, 2022). "In conclusion, the inhibitory effect of metformin on MDSCs and M2 macrophages in the tumor microenvironment of colon cancers is mediated by AMPK activation and subsequent mTOR inhibition, leading to the downregulation of the mevalonate pathway." (PMID 35740547, 2022). "We showed that SIGIRRΔE8 expression promotes the metabolic shift through upregulation of mTOR (suppressing full-length SIGIRR) and/or dysregulation of mitochondrial function (interacting with ATP5A1) to promote survival and proliferation of colon cancer cells." (PMID 35900274, 2022).
colon carcinoma (continued). "It was accompanied by the increased phosphorylation levels of upstream or downstream molecules of mTOR kinase in human colon cancer cells, such as ERK, S6, and mTOR itself." (PMID 35889271, 2022). "In this case, according to our results, for K-RasG13D mutant colon cancer, PI3K/Akt/mTOR or RAS/ERK pathway inhibitor (BEZ235 or SCH772984) alone would be a better treatment option than S7333 alone." (PMID 36386200, 2022). "Therefore, the goal of this review is to present a comprehensive account of current developments on the mTOR pathway and its inhibitors, with an emphasis on the management of microbial infections, the treatment of inflammatory bowel disease, and the management of colon cancer." (PMID 36293326, 2022). "Later, Huo’s group found that Tan IIA stimulated autophagy in the colon cancer cell lines SW480 and HT29 by activating the MEK/ERK/mTOR pathway, thus inhibiting the growth of colon cancer cells." (PMID 36712689, 2022). "Research has shown that in a combinational therapy containing BEZ235, a relatively new inhibitor of the PI3K/Akt/mTOR pathway, and the chemotherapeutic 5-FU, BEZ235 sensitized the HCT-116 colon cancer cells to 5-FU-induced apoptosis." (PMID 34361836, 2021). "They concluded that PAC exhibits anti-colon cancer properties that have potential, by targeting cyclin D1 and suppressing JAK2/STAT3, AKT/mTOR and MEK/ERK signaling pathways as well as their common downstream effector which is cyclin D125." (PMID 34083581, 2021). "PI3K, mTOR (everolimus), and RET (regorafenib) inhibition seem to be synergistic with EGFR (cetuximab) inhibition in selected colon cancers with those activated pathways." (PMID 34885128, 2021). "In AT1.6 and AT6.4 colon cancer cells, treatment with butyrate inhibited cancer cell proliferation by an increase in phospho-AMPKα expression followed by a decrease in phospho-mTOR, resulting in the tumor-suppressive autophagy in AT1.6 colon cancer cells." (PMID 34829834, 2021). "On the other hand, it is thought that autophagy in BR colon cancer cells protects and supports BR colon cancer cells via inducing excessive activation of Akt and inhibition of AMPK phosphorylation and resulting in the induction of mTOR phosphorylation." (PMID 34829834, 2021). "While analysis of spheroidal colon cancer cells showed a diminished activity of AKT, mammalian target of rapamycin (mTOR) and S6K signaling pathways limit its physiologic ability to closely coordinate the tumor areas around vessels in vivo." (PMID 34359827, 2021). "The AMP-activated protein kinase (AMPK) was downregulated along with the activation of Akt and mammalian target of rapamycin (mTOR) and decrease in acetyl-CoA carboxylase (ACC) in BR colon cancer cells compared to those in their respective PT cells." (PMID 34829834, 2021). "Colon cancer decreased microRNA-486 expression, increasing PTEN in tibialis anterior muscle (TA), decreasing the PI3K/mTOR protein pathway, body and muscle wasting, fibers’ cross-sectional area and muscle dysfunction, that were not preserved by AET." (PMID 34830882, 2021). "Taken together, chronic exposure to butyrate increased butyrate resistance in human colon cancer by inducing protective autophagy through the downregulation of AMPK/ACC and activation of Akt/mTOR signaling." (PMID 34829834, 2021). "The purpose of this study was to explore the biological functions of the mTOR and AMPK signaling pathways in colon cancer (CC)." (PMID 34326874, 2021). "PP242 is an ATP-competitive inhibitor of mTOR, and the activity of PP242 in the inhibition of colon cancer growth in vitro and in vivo has been previously reported." (PMID 33067464, 2020).